NUCKS1 (nuclear casein kinase and cyclin dependent kinase substrate 1)
Diseases named in the same sentence as NUCKS1 in open-access papers (continued):
Sharing a sentence is not in itself a finding about the gene and the disease.
colorectal cancer (3 papers, 2021 to 2026). A primary or metastatic malignant neoplasm that affects the colon or rectum. "Thus, it can be concluded that tRF-T36 mimic suppresses human colorectal cancer growth via targeting NUCKS1 both in vitro and in vivo." (PMID 39736854, 2025). "Moreover, further studies that focus on optimizing sequences based on the binding sites in NUCKS1 mRNA complementary to tRF-T36 could greatly enhance the efficacy of siRNAs designed to suppress colorectal cancer (CRC)." (PMID 39736854, 2025).
lymph node metastasis (3 papers, 2009 to 2020). "With regard to the occurrence of lymph node metastasis, NUCKS1 positive expression was observed in 93.4% of cases with lymph node involvement." (PMID 25187794, 2014).
acute lymphoblastic leukemia (2 papers, 2016 to 2018). Leukemia with an acute onset, characterized by the presence of lymphoblasts in the bone marrow and the peripheral blood. "NUCKS1 expression is reduced in adult T-cell leukemia-lymphoma and in childhood acute lymphoblastic leukemia." (PMID 27542204, 2016).
endometriosis (2 papers, 2023 to 2024). The growth of functional endometrial tissue in anatomic sites outside the uterine body. "In a broader context, NUCKS1, a gene associated with cell growth and proliferation, potentially plays a significant role in the advancement of endometriosis." (PMID 38398227, 2024). "Cell viability, invasion and apoptosis are associated with NUCKS1 in endometriosis." (PMID 37582772, 2023). "The regulation of VEGF expression, influenced by NUCKS1 inhibition, is pivotal in promoting angiogenesis within endometriotic tissue and is essential for the development of endometriosis." (PMID 38398227, 2024). "The functional test results are shown that inhibition of NUCKS1 decreased cell viability and capability of invasion, and increased apoptosis in endometriosis cells." (PMID 37582772, 2023). "This indicates that NUCKS1 is highly activated in the ectopic endometrial tissues of EMs patients, suggesting that NUCKS1 plays a very important role in the development and progression of endometriosis." (PMID 37582772, 2023). "Meanwhile, NUCKS1 act through PI3K and NF-κB signaling pathways and cause increased expression of VEGF in endometriosis." (PMID 37582772, 2023). "We have verified that NUCKS1 is involved in the development of endometriosis, but the specific mechanism is unclear." (PMID 37582772, 2023). "To investigate the expression of NUCKS1 in endometriosis, which has similar characteristics with tumor, we collected ectopic endometrium and eutopic endometrium from patients with endometriosis, along with normal endometrial tissues." (PMID 37582772, 2023). "Our research shows that NUCKS1 is highly expressed in endometriosis." (PMID 37582772, 2023). "Reduced expression of PI3K and NF-κB in NUCKS1-inhibited endometriosis cells." (PMID 37582772, 2023). "In this study, We mainly verified that NUCKS1 expression was increased in Endometriosis." (PMID 37582772, 2023). "Therefore, it is worthwhile to explore whether NUCKS1 expression is as different in endometriosis as in tumors." (PMID 37582772, 2023).
gastric adenocarcinoma (2 papers, 2018 to 2020). "Moreover, combined overexpression of NUCKS1 and Ki-67 (a well-known proliferation marker) has been identified as an independent prognostic factor for both disease-free survival and overall survival in gastric adenocarcinoma patients." (PMID 29619377, 2018). "Meanwhile, NUCKS1 has been identified as a candidate gene involved in distant metastasis in colorectal cancer (CRC) and gastric adenocarcinoma." (PMID 29619377, 2018).
hepatocellular carcinoma (2 papers, 2018 to 2023). A malignant tumor that arises from hepatocytes. "For example, NUCKS1 was significantly upregulated in hepatocellular carcinoma and acted as a novel biomarker for the prognosis of patients with hepatocellular carcinoma." (PMID 37528150, 2023). "NUCKS1 is a novel immunohistochemical marker for the early detection of hepatocellular carcinoma (HCC)." (PMID 29619377, 2018).
invasive breast carcinoma (2 papers, 2009 to 2014). A carcinoma that infiltrates the breast parenchyma. "The expression of NUCKS1 in invasive breast carcinoma of no special type has been previously investigated; however, the previous analysis included 26 cases and assessed the associations with the histological grade of tumors and NUCKS1 overexpression only." (PMID 25187794, 2014). "Strong NUCKS1 overexpression was observed in the samples of invasive breast carcinoma of no special type when compared with the adjacent normal tissue." (PMID 25187794, 2014). "The results demonstrated that NUCKS1 was frequently expressed in all the subgroups of non-specific invasive breast carcinoma, with the lowest expression frequency in the luminal A subtype." (PMID 25187794, 2014). "The results confirmed that the expression of NUCKS1 in low grade invasive breast carcinoma of no special type was significantly less common compared with cases of high grade carcinoma." (PMID 25187794, 2014). "Therefore, NUCKS1 may be considered as an additional prognostic marker in the histopathological evaluation of invasive breast carcinoma of no special type." (PMID 25187794, 2014). "Therefore, NUCKS1 may be a novel prognostic marker in the histopathological evaluation of invasive breast carcinoma of no special type." (PMID 25187794, 2014).
lymphoma (2 papers, 2016 to 2021). A malignant (clonal) proliferation of B- lymphocytes or T- lymphocytes which involves the lymph nodes, bone marrow and/or extranodal sites. "Of the 579 overrepresented proteins, six proteins were found in at least 20-fold higher abundance in lymphoma patients (NUCKS1, SLC14A1, GPALPP1, ADPRH, CD72, PRDM15)." (PMID 33562532, 2021). "Of these proteins, the NUCKS1 showed the biggest expression difference between lymphoma and normal B-cells (36.53-fold upregulation)." (PMID 33562532, 2021).
Obesity (2 papers, 2018 to 2022). Accumulation of substantial excess body fat. "The functions of NUCKS1, JADE2 and LOC107986451 in obesity are unknown, and need to explore in the future." (PMID 29966015, 2018).
acute kidney injury (1 paper, 2018). Sudden and sustained deterioration of the kidney function characterized by decreased glomerular filtration rate, increased serum creatinine or oliguria. "In addition, NUCKS1 is reduced in acute kidney injury (AKI), and the inhibition of NUCKS1 plays a role in cytokine modulation and facilitates corneal recovery following alkali burn." (PMID 29619377, 2018).
basal cell carcinoma (1 paper, 2022). A carcinoma involving the basal cells. "In skin tumors, high expression of NUCKS1 in the nuclei of squamous cell carcinoma (SCC) and basal cell carcinoma (BCC) cells is more common than Ki67 expression." (PMID 35069784, 2022).
bipolar disorder (1 paper, 2018). A disorder of the brain that causes unusual shifts in mood, energy, activity levels and the ability to carry out day-to-day tasks. "We identified four rSNP-targeted genes that showed differential expression between patient and control groups depending on brain region: NRAS—in schizophrenia cohort, CDC25B, DDX21 and NUCKS1—in bipolar disorder cohort." (PMID 29745862, 2018). "Two other targeted genes happened to be DE in the anterior cingulate of bipolar disorder patients vs controls: DDX21 (adjusted P-value < 0.00012; logFC = −0.7) and NUCKS1 (adjusted P-value < 0.1; logFC = −0.28)." (PMID 29745862, 2018).
colon cancer (1 paper, 2023). "LncRNA antisense non-coding RNA in the INK4 locus (ANRIL) inhibited the chitooligosaccharide-induced radiosensitivity of colon cancer cells by downregulating miR-181a-5p, and its radiation targets ATM, NIPBL, and NUCKS1 were identified." (PMID 37569824, 2023). "miR-15b-5p improved the radiosensitivity of colon cancer by upregulation, and its radiation targets CCND2, YAP1, and NUCKS1 were identified." (PMID 37569824, 2023).
cyst (1 paper, 2023). A sac-like closed membranous structure that may be empty or contain fluid or amorphous material. "Unfortunately, we failed to further investigate the relationship between NUCKS1 and clinicopathological parameters, such as stage, fertility index, cyst size, and degree of adhesion." (PMID 37582772, 2023).
diabetes (1 paper, 2020). "Among these are genes associated with insulin (MAX, NUCKS1, PIK3R1, PTPN11), diabetes (PIK3R1) and circadian-related processes (HNRNPU, BHLHE41)." (PMID 34745571, 2020).
esophageal cancer (1 paper, 2023). A primary or metastatic malignant neoplasm involving the esophagus. "The overexpression of miR-137 improved the radiosensitivity of esophageal cancer cells, and its radiation targets MAP3K20, RNF4, KDM1A, NIPBL, and NUCKS1 were identified." (PMID 37569824, 2023). "CircPRKCI knockdown inhibited the proliferation and enhanced the radiosensitivity of esophageal cancer cells by upregulating miR-186-5p, and its radiation targets YAP1, NIPBL, and NUCKS1 were identified." (PMID 37569824, 2023).
glioblastoma (1 paper, 2021). The most malignant astrocytic tumor (WHO grade IV). "In particular, the correlation between NUCKS1 and SKP2 is most striking in glioblastoma, kidney renal papillary cell carcinoma, skin cutaneous melanoma, and uveal melanoma." (PMID 34845229, 2021).
glioma (1 paper, 2019). A benign or malignant brain and spinal cord tumor that arises from glial cells (astrocytes, oligodendrocytes, ependymal cells). "The results confirm the differential expression of many transcriptional regulatory proteins that have been already implicated in the pathogenesis of gliomas (HMG proteins -HMGA1, B1 and B2) as well as revealing some novel proteins (NUCKS1 and SON) discussed here." (PMID 31358880, 2019). "Our analysis now reports altered expression of NUCKS1 in gliomas for the first time." (PMID 31358880, 2019).
HIV-1 infection (1 paper, 2014). The type species of lentivirus and the etiologic agent of acquired immunodeficiency syndrome (AIDS). "Therefore, we attempted to link the NUCKS1-induced HIV-1 replication to viral reactivation from latent HIV-1 infection." (PMID 25116364, 2014). "In summary, our study shows that NUCKS1: i) increases the Tat-mediated transcription of the HIV-1 LTR in an NF-κB-independent manner ii) facilitates the interaction of Tat with TAR RNA in the LTR, and iii) plays an important role in the reactivation of latent HIV-1 infection." (PMID 25116364, 2014).
Impaired glucose tolerance (1 paper, 2016). An abnormal resistance to glucose, i.e., a reduction in the ability to maintain glucose levels in the blood stream within normal limits following oral or intravenous administration of glucose.
liver cancer (1 paper, 2023). An epithelial or non-epithelial malignant neoplasm that arises from the liver. "Radiation or miR-30a-5p mimics showed apoptotic effects on liver cancer cells, whereas a combined treatment (radiation and miR-30a-5p mimic) showed synergistic apoptosis, and their radiation target NUCKS1 was identified." (PMID 37569824, 2023). "miR-146a-5p overexpression promoted the apoptosis and radiosensitivity of liver cancer cells, and its radiation targets NUCKS1, YAP1, and RNF4 were identified." (PMID 37569824, 2023).
lung adenocarcinoma (1 paper, 2016). A carcinoma that arises from the lung and is characterized by the presence of malignant glandular epithelial cells. "Interestingly, in mouse lung adenocarcinoma, amplification of a similar region on mouse chromosome 1, which results in elevated expression of several genes including Nucks1, correlates with tumor invasiveness." (PMID 27542204, 2016).
melanoma (1 paper, 2023). A malignant, usually aggressive tumor composed of atypical, neoplastic melanocytes. "Although PRDX6, MAGOHB, NUCKS1, DCAF13, and TXN genes as a panel displayed weak prediction of ICB response, the panel robustly stratified overall survival in patients with melanoma treated with anti-PD1 following progression on anti-CTLA4 therapy." (PMID 37835514, 2023).
metabolic syndrome (1 paper, 2016). A cluster of metabolic risk factors for CARDIOVASCULAR DISEASES and TYPE 2 DIABETES MELLITUS. "In future investigations it therefore will be important to further dissect the role of the NUCKS1 protein in metabolic syndrome and in cancer avoidance to improve both diagnosis and targeted therapy of these prevalent ailments in humans." (PMID 27542204, 2016).
mood disorder (1 paper, 2018). A cognitive disorder a disturbance in which the person's mood is hypothesized to be the main underlying feature. "Overall, NUCKS1 is downregulated in lymphoma, acute inflammatory disease, metabolic diseases, mood disorders, and AIS." (PMID 29619377, 2018). "Moreover, NUCKS1 has been shown to exhibit low expression in a mood disorder group relative to healthy controls (HCs)." (PMID 29619377, 2018).
sarcoma (1 paper, 2023). A usually aggressive malignant neoplasm of the soft tissue or bone. "In addition, we also found that sarcoma patients with relatively high NUCKS1 levels showed lower survival rates than patients with low NUCKS1 levels in the tumors." (PMID 37528150, 2023).
T-cell lymphomas (1 paper, 2016). "Notably, NUCKS1 deficiency in human cells has been linked to a DSB repair defect, and inactivation of NHEJ and HR factors in mice leads to increased tumor burden, frequently resulting from immature T-cell lymphomas." (PMID 27542204, 2016).
thymic lymphoma (1 paper, 2016).
cancer (20 papers, 2007 to 2025). A tumor composed of atypical neoplastic, often pleomorphic cells that invade other tissues. "Across a range of cancer types, mRNAs encoding NUCKS1 and SKP2 display a significant positive correlation." (PMID 34845229, 2021). "The results of our investigation are relevant to many published reports that indirectly have described an association between NUCKS1/NUCKS1 and several human cancer types." (PMID 27542204, 2016). "NUCKS1 contribute to the susceptibility, occurrence, and development of several cancers and other diseases, suggesting that NUCKS1 could be a potent marker for such diseases." (PMID 35069784, 2022). "In addition, a significant association was observed between NUCKS1 immunoreactivity and grading; low grade carcinoma correlates with weaker NUCKS1 expression, as compared with high grade carcinoma." (PMID 25187794, 2014). "Here, we report the first investigation on therapeutics targeting the potent oncogene NUCKS1 to suppress cancer progression." (PMID 39736854, 2025). "In lung cancer, NUCKS1 drives the relentless invasion and proliferation of cancer cells, exacerbating the disease aggressiveness." (PMID 39736854, 2025). "In conclusion, our study reports the first investigation on therapeutics targeting the potent oncogene NUCKS1 to suppress cancer progression." (PMID 39736854, 2025). "Tumors harboring H3-3A::AFF2 and NUCKS1::AFF2 fusions exhibited bland transitional cell-like morphology with acantholytic changes similar to classic DEK::AFF2 carcinoma; the NUCKS1 fusion also demonstrated clear cell features." (PMID 40494991, 2025). "NUCKS1 is not only expressed at increased levels in malignant tumors, but also correlates with the cellular immune activity of tumors." (PMID 37582772, 2023). "Nuclear ubiquitous casein and cyclin-dependent kinase substrate 1 (NUCKS1) has been reported to play an oncogenic role in several cancers." (PMID 37528150, 2023). "NUCKS1 is ubiquitously expressed in all mammalian tissues and has been confirmed to be overexpressed in many cancers, especially malignant neoplasms." (PMID 29619377, 2018). "Although there is still not enough functional information on NUCKS1, evidences suggest that NUCKS1 can be used as the biomarker of several cancers." (PMID 29619377, 2018). "NUCKS1 expression has been found to be much lower in benign keratoacanthoma (KA) than in malignant tumors." (PMID 29619377, 2018). "NUCKS1 is synthesized in the M/G1 phase and is highly expressed in several human cancers including ovarian, lung, bone marrow, brain, and breast cancer." (PMID 25116364, 2014). "These evidences suggest that targeting NUCKS1 holds promise for cancer treatment." (PMID 39736854, 2025). "Studies in recent years have shown that NUCKS1 is upregulated in some types of cancer and may be related to tumorigenesis and progression, so it is considered a potential tumor biomarker and therapeutic target." (PMID 38049814, 2023). "Later, an abnormal expression of NUCKS1 in many malignant tumors was found." (PMID 37582772, 2023). "In addition to cancer, NUCKS1 is highly expressed in tissues from human immunodeficiency virus- (HIV-) positive patients." (PMID 29619377, 2018).
cancer (continued). "Furthermore, considering the overexpression of NUCKS1 in multiple types of tumor, the tRF-T36 mimic could potentially have a broad-spectrum application in cancer therapy." (PMID 39736854, 2025). "Therefore, NUCKS1 can be used as a marker for various cancers." (PMID 29619377, 2018). "Our results demonstrate that circATP9A directly binds with HuR to increase NUCKS1 expression, subsequently activating PI3K/AKT/mTOR signaling and promoting cancer progression." (PMID 38049814, 2023). "Consistent with this notion, the mouse homologous genes of human PRDX6, MAGOHB, NUCKS1, DCAF13, and TXN were upregulated by taxifolin in LL2 LC tumors and facilitated CTL-derived toxicity towards cancer cells." (PMID 37835514, 2023). "Taken together, our results showed that circATP9A can directly bind with HuR to increase the expression level of NUCKS1, further activating PI3K/AKT/mTOR signaling and promote cancer progression." (PMID 38049814, 2023). "However, whether functional loss of NUCKS1 in mice would lead to an increased susceptibility to cancer had not been explored." (PMID 27542204, 2016). "NUCKS1 and SKP2 are overexpressed in most TCGA datasets, including many shared cancer types." (PMID 34845229, 2021). "Even though NUCKS1 seems to be important to the cell cycle and cancer progression, its exact role has not been clarified." (PMID 25116364, 2014). "However, to our best knowledge, targeting NUCKS1 for cancer treatment has not been investigated." (PMID 39736854, 2025). "In this regard, PRDX6, MAGOHB, NUCKS1, DCAF13, and TXN displayed an overall negative correlation with multiple immune checkpoints in LUAD, LUSC, and other cancer types." (PMID 37835514, 2023).